IL10 (interleukin 10)
Diseases named in the same sentence as IL10 in open-access papers (continued):
Sharing a sentence is not in itself a finding about the gene and the disease.
delirium (continued). "Furthermore, differences in serum IL-8, IL-10, and CRP concentrations were associated with postoperative delirium." (PMID 39860413, 2025). "Previous research showed that the anti-inflammatory cytokine IL-10, which is produced by different cells but especially by Treg cells, may regulate the initial pro-inflammatory response in delirium." (PMID 35641947, 2022). "Surface contact between blood and CPB instrument can induce SIRS, which may be involved in the occurrence of delirium after operation through C-reactive protein, IL-1, and IL-10." (PMID 32664963, 2020). "IL-8 was associated with delirium in inflamed patients, whereas IL-10 was associated with delirium in non-inflamed patients." (PMID 24886875, 2014). "In other studies, IL-8, IL-10 and STNFR1 were independently associated with delirium." (PMID 24886875, 2014). "In the noninflamed group of patients (n = 54), IL-8, IL-1ra, IL-10 ratio Aβ1-42/40, and ratio AβN-42/40 were significantly associated with delirium." (PMID 22206727, 2011). "In inflamed patients, the proinflammatory cytokine IL-8 was independently associated with delirium, whereas in noninflamed patients, the ratio Aβ1-42/40 and IL-10 were independently associated with delirium, as determined by multivariate regression analyses." (PMID 22206727, 2011). "In inflamed patients, the proinflammatory cytokine IL-8 was associated with delirium, whereas in noninflamed patients, antiinflammatory cytokine IL-10 and Aβ1-42/40 were associated with delirium." (PMID 22206727, 2011). "After multivariate regression analysis, IL-8 was associated with delirium in inflamed patients, whereas in noninflamed patients, IL-10 and Aβ-42/40 were associated with delirium." (PMID 22206727, 2011). "Additionally, in the subgroup of patients with hypoactive delirium, levels of neopterin and IL-10 were significantly higher than in the mixed-type delirium group (median 111 (IQR 37–111) vs. 29 (IQR 16–64) mg/L, p = 0.004 and median 28 (IQR 12–39) vs. 9 (IQR 4–12) pg/mL, p = 0.001)." (PMID 29801516, 2018). "We have summarized the 13 most studied proteins (IL-6, CRP, IL-8, S100B, IL-10, TNF-a, IL-1b, Cortisol, MCP-1, GFAP, IGF-1, IL-1ra and NFL) about delirium." (PMID 39700095, 2024). "Recent work correlated markers of systemic inflammation and those of astrocyte and glial cell activation (IL-6, IL-8, IL-10, TNF-α, C-reactive protein and S-100β levels) with longer duration of delirium, more severe delirium and higher in-hospital mortality." (PMID 32443606, 2020). "IL-10 has been associated with delirium in non-inflamed, but not in inflamed, critically ill patients; however, we could not find a significant difference in IL-10 levels between delirium and control patients." (PMID 24886875, 2014). "The additional analysis of an association between values of LPS-induced cytokine not normalized for monocyte count and delirium revealed increased release of IL-8 and IL-10 in delirious patients." (PMID 29669581, 2018). "Levels of neopterin (111 (IQR 37–111) vs. 29 (IQR 16–64) mmol/l, p = 0.004) and IL-10 (28 (IQR 12–39) vs. 9 (IQR 4–12) pg/ml, p = 0.001) were significantly higher in patients with hypoactive delirium compared to patients with mixed-type delirium." (PMID 29801516, 2018). "In multivariate regression analysis, IL-8 was independently associated (odds ratio, 9.0; 95% confidence interval (CI), 1.8 to 44.0) with delirium in inflamed patients and IL-10 (OR 2.6; 95% CI 1.1 to 5.9), and Aβ1-42/40 (OR, 0.03; 95% CI, 0.002 to 0.50) with delirium in noninflamed patients." (PMID 22206727, 2011). "Multivariate logistic regression analyses with these biomarkers showed a significant association of ratio Aβ-42/40 (OR, 0.03; 95% CI, 0.002 to 0.50) and the antiinflammatory cytokine IL-10 (OR, 2.6; 95% CI, 1.1 to 5.9) with the presence of delirium in noninflamed patients." (PMID 22206727, 2011).
delirium (continued). "Within-subject analysis showed that levels of IL-6, IL-10 and MCP-1 decreased significantly over time in both groups, but were not different between patients with and without delirium." (PMID 29801516, 2018).
systemic sclerosis (29 papers, 2009 to 2025). A chronic disorder, possibly autoimmune, marked by excessive production of collagen which results in hardening and thickening of body tissues. "Patients with systemic sclerosis also demonstrate a reduction in IL10+ Bregs associated with disease activity." (PMID 38203754, 2024). "Studies have shown that IL10-producing Bregs can suppress skin fibrosis in the Scl-cGVHD (sclerodermatous chronic graft-versus-host disease) model, an animal model of human systemic sclerosis." (PMID 38203754, 2024). "Lower percentages of regulatory T cells, regulatory B cells, natural killer cells (NK-cells), and reduced interleukin-10 (IL-10) secretion are observed in Ssc." (PMID 39210206, 2024). "TLR2- or TLR4-mediated stimulation was also reported to promote DCs to produce IL-10, induce an augmented Th2 immune response, and aggravate systemic sclerosis (SSc)." (PMID 35619184, 2022). "In in vitro experiments using peripheral blood from patients with systemic sclerosis, ibrutinib reduced the production of pro-fibrotic cytokines IL-6 and tumor necrosis factor-α, while preserving the inhibitory role of IL-10, which helps suppress the overactivation of fibrotic functions in B cells." (PMID 39280007, 2024). "Alongside TL1A, experiments adding TGF-β to ILC2 isolated from peripheral blood of subjects with systemic sclerosis that were cultured on dermal fibroblast showed decreased IL-10 production and dramatically decreased KLRG1 expression on ILC2, associated with IL-10 generation." (PMID 37947634, 2023). "Moreover, TGF-β, whose activity is increased in systemic sclerosis, favored the expansion of KLRG1− ILC2s while simultaneously decreasing their production of IL-10 in the skin of systemic sclerosis patients and increasing myofibroblast differentiation." (PMID 36750317, 2023). "In addition, vitamin D induces an increase in IL-10 secretion by regulatory T cells, an effect observed in a study with a patient with systemic sclerosis." (PMID 36555517, 2022). "For instance, in systemic sclerosis (SSc), an autoimmune disease, interleukins such as IL-6, IL-23, IL-10, and IL-17 secreted by B cells or T cells are known to play crucial roles in the pathogenesis." (PMID 39562488, 2025). "In vitro treatment of ibrutinib in peripheral blood from systemic sclerosis reduces IL-6 and TNF-α production, while IL-10 is preserved." (PMID 36521376, 2022). "Elevated levels of IL-10 and enhanced production of IL-10 by alveolar macrophages have been reported in several fibrotic diseases, including IPF and in systemic sclerosis patients with interstitial lung disease." (PMID 23533311, 2013). "IL-10 increased non-significantly, and other studies have found a higher serum level to correlate with RP symptoms in systemic sclerosis patients with newly debuted RP, suggesting its involvement in the early stages of RP." (PMID 38743488, 2024). "In human ILC210s from patients with systemic sclerosis (SSc), treatment with TGF-β dramatically decreased the production of IL-10 and reduced KLRG1 expression, an ILC2 surface marker found to be required for IL-10 production." (PMID 36275689, 2022). "When searching for “systemic sclerosis” and cytokines in the PubMed database, TGF-β had the highest number of hits, followed by IL-6, IL-4, tumor necrosis factor (TNF)-α, platelet-derived growth factor, IL-10, IL-13, IL-1, IL-2, and IL-17 indicating cytokines are related to the pathogenesis of SSc." (PMID 34064515, 2021).
latent infection (28 papers, 2013 to 2025). "For example, CyHV-3 appears to inhibit the host interferon type 1 response required for a robust anti-viral innate immune response (immune suppression) and encodes a functional homologue of IL-10 that is expressed during latent infection (immune evasion)." (PMID 37764923, 2023). "Knockdown of IL-10 induced EBV lytic infection and replication in EBV-associated tumors, further highlighting the role of IL-10 in maintaining long-term EBV latent infection." (PMID 33671917, 2021). "One of the strategies used by EBV to establish latent infections is to produce a viral IL-10 (vIL-10) encoded by the BCRF1 gene, classified as a late gene but expressed in B cells early after infection." (PMID 28316998, 2017). "However, evidence suggests that HCMV harnesses IL-10, both cellular and via virally encoded IL-10 homologues, to drive an immune-dampening phenotype that could enhance both lytic and latent infection." (PMID 25147545, 2014). "Cytokine expression profiles (IL-2, IL-4, IL-6, and IL-10) were analyzed in the latent infection model using flow cytometry." (PMID 40388758, 2025). "The immunosuppressive cytokine IL-10 also plays a role in latent infection, and MCMV expresses an IL-10 orthologue gene during the latent phase." (PMID 32707906, 2020). "The transcript of the UL115.5A region, expressed during latent infection and homologous to interleukin 10 (IL-10), can help the virus escape immune recognition." (PMID 33013768, 2020). "Like HCMV, MCMV can establish a latent infection in cells of the myeloid lineage and these cells are able to respond to IL-10." (PMID 28796839, 2017). "IL-10 is so central to immune response regulation that viruses exploit this pathway to evade immunity and establish persistent/latent infections." (PMID 28316998, 2017). "Cellular IL-10 (cIL-10) homologues encoded by HCMV (vIL-10) are known to be expressed in both lytic and latent infection." (PMID 25147545, 2014). "To determine the impact of active or latent infection or extra-pulmonary dissemination on mycobacterial antigen-specific immunoregulatory cytokine responses, we measured antigen – specific levels of IL-10 and TGFβ." (PMID 23544075, 2013). "In addition to inducing host IL-10 production, the virus encodes a viral IL-10 homolog, UL111A, which is expressed during latent infection and is capable of downregulating MHC class II expression." (PMID 40872232, 2025). "Aside from inducing the expression of human IL-10 during infection, the CMV genome encodes cmvIL10, a human IL-10 homolog whose expression may differ during acute or latent infections." (PMID 34372607, 2021). "With this fundamental understanding, it is predictable and almost trivial that any modulation of the immune control during acute infection, and thus a modulation of viral load, has an impact on MI during latent infection, as exemplified for immune modulation by IL-10." (PMID 32707744, 2020). "We particularly focus on the IL-10 regulatory mechanisms that impact antiviral immune responses and how viruses can use this central regulatory pathway to evade immunity and establish chronic/latent infections." (PMID 28316998, 2017). "The reactivation of latent infection is related to the deregulation of specific immune responses, decreasing inflammatory cytokines such as INF-ɣ and TNF-α associated with increasing Th2 cytokines interleukin 4 (IL4) and interleukin 10 (IL10)." (PMID 28934199, 2017). "We have analyzed the functions of LAcmvIL-10 during latent infection of primary myeloid progenitor cells and found that LAcmvIL-10 is responsible, at least in part, for the known increase in secretion of cellular IL-10 and CCL8 in the secretomes of latently infected cells." (PMID 25253336, 2014). "Our study highlights that a key feature of such a response may be linked to the ability to induce IL17 and IL10 in subjects with latent infection, but not those with disease." (PMID 28931830, 2017).
latent infection (continued). "However, during latent infection decreased levels of IL-6 and elevated levels of IL-10 have been reported which may be the reason for the lower expression of APPs in latently infected individuals." (PMID 26241963, 2015). "Therefore, latent infection is thought to reflect a critical balance between Th1 and Th17 responses that serve to control the pathogen and Th2 cells, regulatory T cells and immunoregulatory cytokines (e.g.,IL-10 and TGFβ) that limit immune-mediated pathology." (PMID 23544075, 2013). "Regardless of T-cell activation, the study also indicates that IL-6, IL-10, and tumor necrosis factor-alpha levels increase during HCMV latent infection." (PMID 40388758, 2025). "In the HCMV latent infection model, PHA group, T-cell group, and FK506 group exhibited significantly increased interleukin (IL)-6, IL-10, and tumor necrosis factor-alpha secretion." (PMID 40388758, 2025). "During latent infection, CMV produces immunosuppressive cytokines such as IL-10 and TGF-β, which can inhibit the cytotoxicity of T lymphocytes and maintain dormancy in host cells." (PMID 38840200, 2024). "In this work we show that there are HCMV-specific IL-10 CD8+ T-cell responses in a cohort of individuals aged 23–76 years of age, predominantly directed against the HCMV proteins known to be expressed during latent infections as well as towards the proteins US3 and pp71." (PMID 36558866, 2022). "However, the fact that HCMV also expresses an IL-10 isoform specific to latent infection (LAcmvIL-10) suggests that certain additional functions not common to cmvIL-10 are required specifically during latency." (PMID 25253336, 2014). "Our experimental findings demonstrate significant upregulation of IL-6, IL-10, and TNF-α in the latent infection model, independent of T-cell activation status." (PMID 40388758, 2025).
steatosis (28 papers, 2010 to 2026). Increased lipid within the cytoplasm of cells. "One-way ANOVA showed that serum IL-10 was 4-fold less in severe steatosis than in mild steatosis (p = 0.038), whereas TNF-α levels increased twice in severe steatosis compared to no steatosis (p = 0.029)." (PMID 42195075, 2026). "An important role is played by IL-10/IL-17A and IL-10/IL-22 relations in the progression from simple MASLD steatosis to advanced MASLD inflammatory steatosis." (PMID 40918132, 2025). "Consistent with this, low-dose hgd40 increased the expression of IL-10, suggesting anti-inflammatory activity that can influence steatosis." (PMID 41514930, 2025). "The study found that although IL-10(−/−) mice were resistant to hepatocellular injury and steatosis brought on by ethanol or high-fat diet, they were susceptible to an inflammatory response in the liver." (PMID 38535313, 2024). "Most of the measured cytokines had similar concentrations, except for IL-9, IL-10, IL-13 and IL-22, which were significantly lower in patients with steatosis." (PMID 39200991, 2024). "Similarly, the reduced concentrations of IL-10 in patients with steatosis observed in our study might indicate that the loss of anti-inflammatory properties of IL-10 significantly contributes to the establishment of steatosis and, possibly, the development of fibrosis." (PMID 39200991, 2024). "In contrast, there were fewer necrotic areas whose extent was reduced in grafts in which steatosis was present from the BD+IL-1ra+LT and BD+IL-10+LT groups." (PMID 37593740, 2023). "The anti-inflammatory Th2 cytokine IL-10 can increase the number of M2-type macrophages, lead to congenital immune imbalance, and eventually lead to hepatocyte steatosis." (PMID 37174318, 2023). "In hepatic grafts from DBDs in which steatosis was present, the same level of administration of NO (BD+NO+LT) did not have an effect and was unable to induce changes in either IL-10 or IL-1β with respect to the experimental group BD+LT, without any treatment." (PMID 37593740, 2023). "Second, there was no detectable IL10 (anti-inflammatory cytokine secretion) in any exposure or time points in the NASH liver MT yet an IL10 response was observed in the steatosis liver MT at the later time-point." (PMID 34668024, 2022). "For instance, treatment with IL-6 ameliorated fatty liver by inducing STAT3 phosphorylation in ob/ob and HFD- induced obese mice, while deletion of IL-6 or hepatic STAT3 resulted in steatosis and hepatocellular damage in IL-10 knockout mice." (PMID 30038584, 2018). "Multiple chemokines and cytokines have been implicated in the development of steatosis and the progression to NASH; including IL-6, TNF-α, MCP-1 and IL-10." (PMID 24039859, 2013). "Interestingly, the level of IL-10 [MFI in CD4+] and IL-10 [MFI in CD4+CD25+] differentiated patients with simple steatosis in early MASLD from advanced MASLD patients (p < 0.01, p < 0.02, respectively)." (PMID 40918132, 2025). "For this, we evaluated whether the increased IL-1β levels were responsible for the exacerbated damage induced by the inhibition of either IL-6 or IL-10 action in liver grafts from DBDs, in the absence and presence of steatosis, respectively." (PMID 37593740, 2023). "However, when steatosis was present, we observed reduced levels of IL-10 in the BD+LT group, compared to the LT group." (PMID 37593740, 2023). "However, when steatosis was present, a progressive reduction in the levels of IL-10 was observed as the reperfusion time proceeds." (PMID 37593740, 2023). "Finally, the association shown an interesting activity increasing the anti-inflammatory interleukin 10 (IL 10) cytokine expression (four times in respect to the steatosis control)." (PMID 36770927, 2023). "In the mentioned studies, the serum IL-10 progressively decreases with the level of steatosis." (PMID 28852433, 2017).